FAM13A-AS1 (FAM13A antisense RNA 1)
Synonyms: NCRNA00039; formerly FAM13A1OS; FAM13AOS
Gene: Long non-coding RNA gene on chromosome 4 (88,708,622 to 88,730,103, forward strand). Ensembl gene ENSG00000248019.
Diseases named in the same sentence as FAM13A-AS1 in open-access papers:
FAM13A-AS1 is named in the same sentence as 2 diseases in open-access papers, as found by Europe PMC text mining. Sharing a sentence is not in itself a finding about the gene and the disease. The quoted sentences say what the papers report.
bladder urothelial carcinoma (1 paper, 2022). "Furthermore, FAM13A-AS1 (FAM13A antisense RNA 1), which is associated with autophagy, is included in the lncRNA signature to predict the prognosis of thyroid cancer and bladder urothelial carcinoma." (PMID 35903713, 2022).
FAM13A-AS1 also shares sentences with these, for which no sentence is quoted: thyroid cancer (1 paper).